ORAI1 (ORAI calcium release-activated calcium modulator 1)
Diseases named in the same sentence as ORAI1 in open-access papers (continued):
Sharing a sentence is not in itself a finding about the gene and the disease.
breast cancer (continued). "For instance, Orai1 is over-expressed in a number of breast cancer cell (BCC) lines, which display a significantly higher SOCE compared to control cells." (PMID 23049731, 2012). "There is increasing evidence suggesting that ORAI1, components of store-operated calcium channel, play a pivotal role in breast cancer progression and metastasis." (PMID 22778704, 2012). "As ORAI1 and TRPC1 regulate ERK1/2 activity in other cell types we assessed constitutive ERK1/2 phosphorylation in MDA-MB-468 breast cancer cells with ORAI1 or TRPC1 silencing." (PMID 22666335, 2012). "Previous studies reported the role of Orai1 in constitutive Ca2+ entry in breast cancer cells." (PMID 39303919, 2024). "Both Orai1 variants are overexpressed in MCF7 and MDA-MB-231 breast cancer cells." (PMID 39303919, 2024). "Thus, we focused our study on the role of Orai1 variants in SPCA2-triggered constitutive Ca2+ entry and its role in microcalcification in breast cancer cells." (PMID 39303919, 2024). "In addition, recent data suggest that ORAI3 plays crucial role in calcium regulation of ER + breast cancer cells in particular, and is capable of complexing with ORAI1 to form heteromultimeric channel." (PMID 37400769, 2023). "The activation of Akt increased Ca2+ entry via Orai1 in human breast cancer cells." (PMID 37759164, 2023). "Over-expression and activation of Orai1 have been reported in breast cancer." (PMID 36109490, 2022). "Given the upregulation of ORAI1 in basal breast cancer cells, our results provide further evidence that ORAI1 may contribute to cancer progression through regulation of gene expression." (PMID 35682546, 2022). "Altogether, these results suggested that NCL was a novel binding partner of Orai1, and the interaction may contribute to the progression of breast cancer." (PMID 36109490, 2022). "However, the role of ORAI1 in the regulation of transcription in breast cancer cells of the basal molecular subtype is still unclear." (PMID 35682546, 2022). "Here we report that expression of a glycosylation-deficient Orai1 mutant (Orai1N223A) in Orai1KO luminal breast cancer MCF7 cells and TNBC MDA-MB-231 cells, as well as in non-tumoral breast epithelial MCF10A cells, is not essential for the activation of SOCE." (PMID 36612199, 2022). "However, there has been no comprehensive assessment to identify the genes that are regulated by ORAI1 in breast cancer cell lines." (PMID 35682546, 2022). "Orai1 and 3 play different roles in distinct breast cancer subtypes since Orai1 signalling pathway alterations may be characteristic of poorest prognosis in basal cancer subtype." (PMID 35163823, 2022). "We also investigated whether Orai1 peptides performed the inhibitory effect on the proliferation of breast cancer cells." (PMID 36109490, 2022). "For instance, Orai1 may have an oncogenic effect in breast cancer cells since reduced Orai1-mediated Ca2+ influx decreased cellular proliferation and migration." (PMID 36310590, 2022). "Indeed, an elevated expression of the ORAI1 calcium channel is a feature of basal-like breast cancers, where its expression is critical for breast tumor cell migration and metastasis." (PMID 35682546, 2022). "In this study, we found that NCL could interact directly with Orai1 inducing calcium influx and promoting breast cancer cells proliferation." (PMID 36109490, 2022). "Moreover, the Orai1 channel is a well-known regulator of proliferation and migration in breast cancer cells." (PMID 36498894, 2022). "Taken together, our results suggested that the C-terminus of NCL interacts with Orai1 to activate Ca2+ influx, which may alter calcium-regulated signal and contribute to breast cancer progression." (PMID 36109490, 2022). "In order to further investigate potential activation mechanisms of Orai1 involved in the development of breast cancer, biotinylated Orai1-NT or CT peptides were synthesized, and a biotin-based pull-down assay was performed to identify the proteins interacting with Orai1." (PMID 36109490, 2022).
breast cancer (continued). "Elevated ORAI1 expression is a feature of basal breast cancer cells." (PMID 35682546, 2022). "Using a combined approach of gene disruption and rescue experiments, we sought to identify the genes regulated by ORAI1 in basal breast cancer cells, their dependence on Ca2+ influx and STIM1 binding, and their association with the translocation of transcription factors." (PMID 35682546, 2022). "Blockage of Orai1-NCL interaction attenuates breast cancer cells growth in vitro and in vivo." (PMID 36109490, 2022). "This suggests that SK3–Orai1 expressing cells generate small, constitutive Ca2+ entry, in line with the previously reported enhanced Ca2+ levels in breast cancer cells compared to healthy breast cells, likely due to a unique interplay of SK3 and Orai1 in cancer cells." (PMID 34944977, 2021). "In addition to promoting the migration and invasiveness of renal cancer cells, the upregulated expression of TRPC6 is also required for translocation of Orai1 and Orai3 to the plasma membrane of metastatic breast cancer cells." (PMID 36046433, 2021). "Disruption of Ca2+ signalling by aberrant expression or activity of these two groups of calcium channels is well established in various cancer types, such as the role of Orai1 in breast cancer metastasis and T-type Ca2+ channels in breast cancer cell proliferation." (PMID 34208665, 2021). "The relevance of Orai1 in breast cancer cell function has been widely demonstrated." (PMID 33916304, 2021). "Similarly, the Boyden chamber assay performed with breast cancer cells showed that ORAI1 knockdown decreased their migration level." (PMID 34831241, 2021). "Moreover, transient receptor potential canonical 6 (TRPC6) channel has been reported to regulate plasma membrane translocation of Orai3 as well as Orai1 in breast cancer cell line." (PMID 34360783, 2021). "Interestingly, in analogy to SK3, SPCA2 has been reported to induce constitutive Ca2+ entry via Orai1 in breast cancer cells in a STIM1-independent manner." (PMID 33333945, 2020). "In breast cancer, SigR1 in the MAM is upregulated and favors cell migration by regulating Ca2+ homeostasis in association with the SK3 channel (calcium-activated K+ channel) and Orai1." (PMID 32784704, 2020). "Moreover, microarray analysis data show that, the basal-breast cancer, a breast cancer subtype with a very dismal prognosis, is correlated with an altered relationship between the ORAI1 activators STIM1 and STIM2, characterized by high STIM1/STIM2 ratios." (PMID 32733237, 2020). "The SKF-96365 was the first ORAI1 blocker used in cancer studies, specifically breast cancer." (PMID 32733237, 2020). "Alternatively, the positive association between ORAI1 and NCS‐1 may be due to their association with breast cancers of the basal molecular subtype." (PMID 31647602, 2020). "Moreover, knockdown of ORAI1 or STIM1 in breast cancer cells led to reductions in in vitro migration and invasion and in vivo metastasis." (PMID 33569087, 2020). "Interestingly, also STIM1-independent Orai1 activation mechanisms have been detected in breast cancer cells." (PMID 33333945, 2020). "ORAI1 is a well-characterized regulator of the proliferation and migration of many basal breast cancer cells; however, the role of ORAI3 in these types of breast cancer cells remains unclear." (PMID 30754719, 2019). "A dysregulated STIM1/Orai1/SOC axis is implicated in many pathological conditions such as SCID (severe combined immune deficiency syndrome); cardiovascular and pulmonary diseases; and cancer of the breast, colon, and, esophagus." (PMID 31226817, 2019). "Moreover, Orai1 silencing can reverse the antiapoptotic effects of collagen in breast cancer MCF-7 and T47D cells." (PMID 31252656, 2019). "Hence, further studies are required to define the mechanism by which ORAI1 levels are elevated in basal breast cancers." (PMID 30754719, 2019).
breast cancer (continued). "Breast cancers with high ORAI3/low ORAI1 were associated with poorer RFS in basal, ERα-negative and TNBCs, and low ORAI3/high ORAI1 associated with good outcome." (PMID 30754719, 2019). "Furthermore, Ca2+ entry through ORAI1-mediated Ca2+ channels plays a critical role in the migration and metastasis of breast cancer cells." (PMID 31627357, 2019). "Moreover, silencing and pharmacological inhibition of ORAI1 in basal/triple negative MDA-MB-231 breast cancer cells reduces their invasiveness in vitro and in vivo." (PMID 30754719, 2019). "Our results indicated that both Orai1 variants were highly expressed in the breast cancer MCF7 and MDA-MB-231 cell lines as compared to non-tumoral MCF10A cells (p < 0.05; n = 6)." (PMID 31652779, 2019). "Moreover, Kv10.1 regulates also the serum-induced migration in MDA-MB-231 mammary cancer cells via a Ca2+ entry through Orai1 channel." (PMID 29872495, 2018). "Expression of the TRPC6dn significantly attenuated the interaction of TRPC6 with the Orai channels in MCF7 and MDA-MB-231 cells (p < 0.05; n = 4), thus suggesting that TRPC6 channel function is essential for its interaction with Orai3 in MCF7 and Orai1 in MDA-MB-231 breast cancer cells." (PMID 30223530, 2018). "However, SOCE in less aggressive, estrogen receptor positive luminal subtype of breast cancer cells occurs mainly through ORAI3, and upon loss of estrogen receptor alpha, metastatic cells appear to switch to SOCE through the ORAI1 channel." (PMID 30034631, 2018). "For instance, Orai1 appears to be upregulated in the poor prognosis basal breast cancer molecular subtype, and silencing of ORAI1 reduces the proliferation of breast cancer cell lines in vitro and in vivo, the invasiveness of MDA-MB-231 breast cancer cells in vitro, and metastasis in vivo." (PMID 30034631, 2018). "In vitro studies have reported that SOCE inhibition leads to MDA-MB-231 breast cancer cells with slower focal adhesion turnover rates, which indicates that Ca2+ influx through STIM1 and Orai1 is essential for focal adhesion assembly and disassembly in breast cancer cells." (PMID 30558192, 2018). "Furthermore, STIM1 or Orai1 was found to be over expressed in tumor tissues when compared with pre-cancerous tissues in breast cancer patients." (PMID 27199756, 2016). "Based on a published data set of 345 female breast cancer patients and 290 female controls, we used a particle swarm optimization (PSO) algorithm to identify the possible protective models of breast cancer association in terms of the SNPs of ORAI1 gene." (PMID 26380267, 2015). "ORAI1 channels play an important role for breast cancer progression and metastasis." (PMID 24685237, 2014). "Consistent with the pro-migratory role of STIM1 and Orai1, suppressed expression levels of STIM1 and Orai1 in highly metastatic breast cancer cells inhibited lung metastasis after tail vein injection in immunodeficient SCID mice, which can be mimicked by pharmacological inhibitor SKF96365." (PMID 23594099, 2013). "The results from immunofluorescent staining and surface biotinylation in breast cancer cells showed that SPCA2 is partially localized to the plasma membrane where it interacts with the N-terminus of SOC channel Orai1 to elicit the constitutive STIM1-independent Ca2+ influx." (PMID 23594099, 2013). "Furthermore, inhibition of ORAI1 in invasive MDA-MB-231 breast cancer cells reduces serum-induced migration in vitro and metastasis formation in vivo." (PMID 22666335, 2012). "Hence, further study is needed to investigate if there is a link between ORAI1 gene expression and inflammation status of breast cancer patients." (PMID 22778704, 2012). "Although a recent study has identified the crucial role of ORAI1 in breast cancer cell migration and metastasis, the association between genetic variations of ORAI1 and the risk of breast cancer is not known." (PMID 22778704, 2012). "Silencing of ORAI1 inhibited ATP-stimulated Ca2+ entry in MDA-MB-468 breast cancer cells." (PMID 22666335, 2012).
breast cancer (continued). "Furthermore, results obtained from ORAI1 knockdown cells indicated a reduction of cell proliferation in both endothelial and breast cancer cells." (PMID 22253717, 2012). "An increase in Orai1, but not Stim1, levels has also been reported in several breast cancer cell (BCC) lines, while the loss of Stim1 protein prevents SOCE activation in Wilms tumor cells." (PMID 23049731, 2012). "As a result, Orai1α is the only Orai1 variant responsible for in vitro calcification mediated by SPCA2 in MCF-7 cells, which suggest that Orai1α might be considered as a specific therapeutic target in the treatment of ER+ breast cancer." (PMID 39303919, 2024). "Therefore, the SOCE-dependent cAMP signaling might have increased importance in breast cancer biology since both Orai1 and AC8 have been found to be highly expressed in these cells." (PMID 36498894, 2022). "Hence, targeting the ORAI1/STIM1 function in basal breast cancer cells could lead to a decrease in overall inflammatory signals through its effect on IL6 and PTGS2 expression." (PMID 35682546, 2022). "Thus, in triple negative breast cancer cells, such as MDA-MB-231 cells, SOCE has been reported to be strongly dependent on STIM1 and Orai1, with TRPC6 playing a relevant role in the surface expression of Orai1, while in luminal breast cancer cells SOCE is mostly mediated by STIM1, STIM2, and Orai3." (PMID 33916304, 2021). "Besides Orai1, Orai3 seems to play a role in breast cancer development." (PMID 33333945, 2020). "Additionally, SK3 and Orai1 in breast cancer cells have been determined via immuno-colocalization." (PMID 33333945, 2020). "Similarly, SOCE could be reduced with knockdown of ORAI1 or STIM1 in breast cancer cells, but which also led to reductions in in vitro migration and invasion and in vivo metastasis." (PMID 33569087, 2020). "For example, in some prostate cancer cells, reduced ORAI1-mediated Ca2+ influx occurs and may bestow resistance to some apoptotic pathways, whereas in some breast cancer cells, augmentation of ORAI1-mediated Ca2+ influx appears to contribute to migration and proliferation pathways." (PMID 30754719, 2019). "Moreover, high ORAI3/ORAI1 ratio was shown to correlate with poor prognosis in breast cancer." (PMID 31010205, 2019). "However, the protective association of breast cancer in terms of combinational SNPs of ORAI1 gene was not investigated in SNP-SNP interaction manner." (PMID 26380267, 2015). "However, the possible SNP-SNP interactions of ORAI1 gene associated with breast cancer were not addressed." (PMID 24685237, 2014). "The scenario becomes even more complicated when considering that Orai3 is activated by Stim1 upon intracellular store depletion in some oestrogen receptor-positive breast cancer lines, and that Orai1 may assemble into a supramolecular ternary complex with Stim1 and TRPC1." (PMID 25126575, 2014). "Further studies on breast cancer cells revealed SPCA2 overexpression in the plasma membrane, where it directly activates Orai1 independently of STIM1." (PMID 41226294, 2025). "In the case of other tumours that remain under the control of oestrogen, such as mammary tumours, SPCA can cooperate with Orai1 to activate STIM1-independent calcium entry, which promotes breast tumorigenesis." (PMID 41226294, 2025). "We show that only the mammalian-specific Orai1α rescues SPCA2-dependent constitutive Ca2+ entry in Orai1-KO MCF7 cells, a widely used luminal breast cancer cell line." (PMID 39303919, 2024). "E-Syt1 and E-Syt2 are required for full activation of SOCE in ER+ breast cancer MCF7 cells and the TNBC cell lines MDA-MB-231 and BT20, most likely by supporting the close apposition of Orai1 and STIM1 in ER–PM junctions." (PMID 39061158, 2024). "One of the early studies shows that Orai1 and STIM1, which mediate extracellular calcium influx into ER via store‐operated calcium entry (SOCE), were critical for breast cancer cell metastasis." (PMID 36453019, 2023).
breast cancer (continued). "ORAI1 is responsible SOCE-regulated calcium entry in a variety of cell types, and ER + breast cancer cells used in this study were reported to show normal or decreased ORAI1 expression." (PMID 37400769, 2023). "It is worth to mention that both CHX and tunicamycin have a smaller effect in MDA-MB-231 cells than in MCF10A cells, thus suggesting that Orai1 and STIM1 protein degradation is slower in MDA-MB-231 breast cancer cells." (PMID 36612199, 2022). "In ER+ breast cancer cells, SOCE is mediated exclusively by Orai3 and STIM1/STIM2, whereas in ER- breast cancer cells, the canonical CRAC channel consists of STIM1/Orai1, which is sufficient to trigger SOCE." (PMID 36612099, 2022). "Using CRISPR-Cas9 gene editing, ORAI1 protein expression was disrupted in MDA-MB-231 and MDA-MB-468 basal breast cancer cells." (PMID 35682546, 2022). "Dysfunction of STIM1/Orai1-mediated SOCE has been found in various tumor types, including breast cancer." (PMID 36109490, 2022). "AC8 and Orai1 interact to trigger the phosphorylation of Orai1 in MDA-MB-231 TNBCs, which results in inactivating Orai1 and stimulating breast cancer migration." (PMID 35832555, 2022). "Orai1 inhibitor 2-APB can significantly inhibit NCL-meditated calcium influx and abolish the promoting effects of NCL on breast cancer cells proliferation." (PMID 36109490, 2022). "The reversal of EMT in a highly aggressive type of breast cancer depends on the enhanced expression of SPCA2, which triggers constitutive Ca2+ influx via Orai1." (PMID 36612099, 2022). "In the treatment of cancer, SKF-96365, a SOCE/Orai1 blocker, has been shown to impair cell proliferation of GBM cells in vitro and metastasis of breast cancer cells in vivo." (PMID 36612099, 2022). "In the breast cancer cell line, MCF-7, a novel STIM1-independent mechanism for triggering Ca2+ entry through Orai1 activation via the accessory protein Secretory Pathway Ca2+-ATPase 2 (SPCA2) has been identified." (PMID 36612099, 2022). "Our findings reveal a new activation mechanism of Orai1 and new functions of NCL, which provide a new strategy in breast cancer treatment." (PMID 36109490, 2022). "In breast cancer cells, the SK3-Orai1 co-regulation was reported to result in constitutive Orai1 dependent but STIM1 independent Ca2+ influx." (PMID 35327543, 2022). "More importantly, the synthesized Orai1 peptide specifically targeting NCL and blocking NCL-Orai1 interaction, attenuates the growth of breast cancer cells through the reduction of NCL-meditated SOCE." (PMID 36109490, 2022). "Next, we explored the role of Orai2 in TG-induced SOCE in the breast cancer cell lines that exhibit low (SKBR3 and BT20) or high (T47D) Orai1:Orai2 expression ratios." (PMID 35008277, 2021). "This was first assessed in the context of breast cancer where STIM1 and Orai1 were shown to be important for breast cancer cell migration and metastasis to the lung using xenograft mouse models." (PMID 34069353, 2021). "Among the exceptions are ER+ breast cancer cells and NSCLC cells, where SOCE is strongly dependent on the Orai3 expression, while knockdown of Orai1 or Orai2 has a minor effect if any, meaning that Orai3 plays a predominant role in SOCE in these cells." (PMID 34768857, 2021). "In this regard, Orai1 and SPCA2 were reported to be expressed at aberrant levels in some breast cancer tissues with overexpression patterns correlating with cancer aggressiveness." (PMID 33466526, 2021). "A recent study has revealed the role of Orai1, together with the channel Kv10.1 and the secretory pathway Ca2+-ATPase-2 (SPCA2), in collagen-induced breast cancer cell survival." (PMID 33916304, 2021). "As the effects of these novel compounds were investigated on native SOC of breast cancer cells (MDA-MB-231) and HEK 293 cells, their effects on Orai1 and Orai3 individually remain of interest to determine potential isoform-specificity." (PMID 34360783, 2021).